MYCN (MYCN proto-oncogene, bHLH transcription factor)
Diseases named in the same sentence as MYCN in open-access papers (continued):
Sharing a sentence is not in itself a finding about the gene and the disease.
medulloblastoma (continued). "Together these studies in Grp3 MB and NB suggest that inhibition of HDACs may also be efficacious in MYCN-driven medulloblastoma." (PMID 34195095, 2021). "SHH is the predominant group in adult medulloblastomas, and adult SHH tumours are characterised by upstream pathway mutations in PTCH1 and SMO, whereas downstream pathway alterations such as SUFU mutations and MYCN amplifications are rare in this age group." (PMID 33172502, 2020). "In contrast, WTC10 MYCN tumors clustered with SHH medulloblastoma." (PMID 31204176, 2019). "Thus, the human WTC10 MYCN tumor model of medulloblastoma recapitulates the specific tumor subtype and epigenetic profile more accurately than the MYCN GEMM." (PMID 31204176, 2019). "We transduced NES cells with MYCN, observing medulloblastoma upon orthotopic implantation in mice." (PMID 31204176, 2019). "Transactivated by HIF-1α, MYC is a prominent biological determinant in SHH (MYCN) and group 3 (MYCC) medulloblastoma but has not been widely implicated in group 4 biology, although MYCN amplifications are infrequently observed." (PMID 29880060, 2018). "We present the case of a young boy with group three MYCN-amplified medulloblastoma." (PMID 29343221, 2018). "Although a smaller set of tumors from the GTML model shows a resemblance to Group 4 medulloblastoma and MYCN-driven postnatal stem cells give rise to tumor cells that are positive for the Group 4 KCNA1 marker, there are as yet no reliable Group 4 models for medulloblastoma." (PMID 28333115, 2017). "MYCN is important in cell cycle progression and apoptosis and it is the dysfunction of these processes due to amplification of the MYCN gene that contributes to aggressive medulloblastoma." (PMID 28358317, 2017). "Interestingly, MYCN drives either SHH-dependent or SHH-independent medulloblastoma as a consequence of the timing of its oncogenic expression from embryonic or postnatal cerebellar stem cells, respectively." (PMID 28333115, 2017). "The collaboration of SHH and MYCN may be pivotal in both medulloblastoma and basal cell carcinoma regulation, and further insights are necessary for the identification of potential novel therapeutics." (PMID 28358317, 2017). "We efficiently induced bioluminescent medulloblastomas expressing eGFP-luciferase in BarTeL mice by infection of a limited number of somatic cGNPs with avian retroviral vectors encoding the active N-terminal fragment of SHH and a stabilized MYCN mutant." (PMID 27310018, 2016). "Interestingly, CD15 (SSEA-1/Lex), a putative marker for medulloblastoma in Ptc1 mutant mice, also displayed elevated and distributed staining profiles upon MYCN withdrawal." (PMID 25785590, 2015). "Similar as MYCC only ~ 5% of medulloblastomas harbor MYCN amplification." (PMID 23618424, 2013). "Thus, to date available data do not support a predictive value of MYCN gene amplification status in the whole medulloblastoma cohort, and refinement of the definition of MYCN amplified tumors by using additional clinical and molecular parameters is needed." (PMID 23618424, 2013). "Thus, PTPRD is likely to have a tumor suppressor function in any type of cancer with MYCN amplification, including other pediatric cancers such as medulloblastoma and rhabdomyosarcoma, or in adult tumors that are dependent on high AURKA levels." (PMID 22305495, 2012). "Nor did we detect an association between MYCN expression and overall survival in the larger group of 64 medulloblastomas." (PMID 16968546, 2006).
medulloblastoma (continued). "To further validate our finding that MNA+ cancers may deploy a GREB1-dependent mechanism to drive expression of pro-oncogenic genes such as MYO1B, independently of MYCN, we investigated medulloblastoma (MB), a childhood brain tumor that also harbors recurrent MNA." (PMID 37611092, 2023). "The oncogenic effect of mutations in the fusion genes such as ARID1A, PVT1, GFI1, MYCN, DNMT1, and TET3 has been identified in various tumors including medulloblastomas to regulate tumorigenesis, suggesting that the predicted inframe fusion proteins may possess oncogenic potential." (PMID 33681213, 2021). "Finally, the SIOP-Europe high-risk medulloblastoma trial is using molecular screening to identify appropriate cases for increased-intensity treatments, including MYC/MYCN amplification (excluding MYCN amplified Group 4 MB) and SHH-alpha MB (EudraCT Number: 2018-004250-17)." (PMID 34885207, 2021). "This bias toward neuronal lineages may explain why transformed NES cells (both Gorlin and MYCN driven) resemble medulloblastoma more than other brain tumor types thought to be derived from glial lineages such as glioblastoma, ependymoma, and pilocytic astrocytoma." (PMID 31204176, 2019). "However, ectopic expression of either human c-MYC or MYCN (mutationally stabilized and wild-type) in conjunction with SHH expression in Nestin-expression progenitor cells generated SHH medulloblastoma at a significantly increased incidence compared with infection with RCAS-SHH alone." (PMID 28333115, 2017). "These include enhancers of regulators of genes that drive glutamatergic neuronal identity (e.g., PAX6, WLS), and known drivers of medulloblastoma (OTX2, MYCN, CBFA2T2)." (PMID 41279093, 2025). "Group 3/4 medulloblastoma with MYC, MYCN or PRDM6 alterations have complex subclonal structures, with each subclone having unique properties." (PMID 40335697, 2025). "Interestingly, group 3/4 medulloblastomas with amplification of MYC or MYCN or duplicated SNCAIP had significantly higher SNV densities at both ECA and MRCA than the remaining tumours, suggesting that later onset of (pre-)malignancy may predispose to the subsequent acquisition of these drivers." (PMID 40335697, 2025). "In these cells, the gene and signaling pathways that are common to several medulloblastoma lineages have been identified, such as NRP1, MSI1, TWIST1, MYCN, and OX2." (PMID 36982406, 2023). "Notably, the combination of CD532, which disrupts the interaction between AURK and MYCN, and verteporfin, a YAP inhibitor, was associated with a dramatic suppression of tumor growth both in vitro and in vivo and an increased survival of SHH-activated medulloblastoma-bearing mice." (PMID 37568705, 2023). "Entities with recurrent alterations of MYCN and CREBBP are for example medulloblastoma and malignant glioma." (PMID 37407554, 2023). "Compared to MYCN-expressing brain tumors driven from the same promoter, pronounced ARF silencing is present in our MYC-expressing model and in human medulloblastoma." (PMID 36869047, 2023). "Studies in medulloblastoma have indicated that MYCN binds MIZ-1 with a lower affinity compared with MYC, with consequences for MIZ-dependent repression in different subtypes of medulloblastoma." (PMID 37175848, 2023).
medulloblastoma (continued). "Treatment with PRMT5 inhibitor EPZ015666 resulted in decreased MYC protein levels and medulloblastoma cell growth, indicating that PRMT5 inhibitors are potential treatments for MYCN-driven cancer." (PMID 36770809, 2023). "Beyond NB, this therapeutic approach can be of broader relevance for therapy of MYC/MYCN-addicted cancers, as we have previously shown a synergistic antitumor efficacy of BET/mTOR inhibitors in MYC-driven medulloblastoma." (PMID 34565342, 2021). "While numerous studies have demonstrated a key role of MYCN in NB and GBM metabolism, its metabolic function in medulloblastoma still remains elusive." (PMID 34195095, 2021). "Because non-MYCN-amplified NB cell lines, including SK-N-AS, express MYC which is a target for combined BET/mTOR in medulloblastoma cells." (PMID 34565342, 2021). "Although most SHH medulloblastomas highly express MYCN, the few SHH (or SHH-like) medulloblastoma cell lines (UW-228-2 and DAOY) prominently express only MYC, similar to most Group 3 medulloblastomas." (PMID 33425720, 2020). "SOX9 has been reported as a critical transcription factor in MYCN Proto-Oncogene, BHLH Transcription Factor, MYCN-driven medulloblastoma and can be related to drug resistance of these tumors." (PMID 32508873, 2020). "Among the four molecular subgroups of medulloblastomas, Group 3 tumors carrying MYC /MYCN amplification are the most aggressive tumors with the worst prognosis." (PMID 32410663, 2020). "Treatment with the PRMT5 inhibitor EPZ015666 results in a decrease of MYC protein levels and medulloblastoma cell growth, which suggests that PRMT5 inhibitors are potential therapeutics for MYC- and MYCN-driven cancers." (PMID 33628735, 2020). "The transcriptome of GTML GEMM tumors aligned with group 3 medulloblastoma, a subgroup in which patient tumors commonly amplify CMYC and only rarely amplify MYCN." (PMID 31204176, 2019). "Histological analysis revealed an embryonal neoplasm with anaplastic features and immunopositive for synaptophysin, a neuronal marker characteristic of human medulloblastoma, and for FLAG-tagged MYCN." (PMID 31204176, 2019). "Misexpression of MYCN in both otherwise-normal NES cells and PTCH1+/− NES cells derived from patients with Gorlin syndrome each generated medulloblastoma in mice." (PMID 31204176, 2019). "In support of WTC10 MYCN tumors representing SHH medulloblastoma, WTC10 MYCN tumors, compared to parental NES cells, showed increased expression of ATOH1, a marker of GNP cells, a cell of origin for SHH medulloblastoma." (PMID 31204176, 2019). "Such a reciprocal activation is also reported between PLK1 and MYCN, one of the well-known genes highly expressed in SHH medulloblastomas." (PMID 31185958, 2019). "Gene amplifications are rare in medulloblastomas, but when they occur very frequently concern either the MYC or the MYCN oncogenes." (PMID 30279357, 2018). "This analysis carried out on a large number of medulloblastomas showed frequent MYC amplifications in Group 3 and WNT medulloblastomas; in contrast, MYCN amplifications were frequent in SHH and Group 4 tumors." (PMID 30279357, 2018). "The MYC genes are often overexpressed or amplified in medulloblastoma, with differential expression of c-MYC and MYCN among the four subgroups." (PMID 28333115, 2017). "Establishment of their wider relevance to medulloblastoma at diagnosis, alongside other MYC/MYCN amplified and overexpressing malignancies, is paramount." (PMID 25533335, 2015). "In contrast, MYCN amplification, mostly occurring in SHH or Group 4 medulloblastomas, is still prognostic in both of these subgroups, but did not hold up in the multivariate analyses." (PMID 22358457, 2012).
medulloblastoma (continued). "High-level gene amplifications are overall rarely observed in medulloblastoma, but when they do occur, they most frequently affect the MYC or MYCN oncogenes and only in a very few cases the related MYCL gene." (PMID 22358457, 2012). "Also, the interactions between MYCN and the SHH signaling raises the possibility of combined SHH/MYCN-targeted therapies, similar to those used in SHH-subgroup medulloblastomas." (PMID 40365336, 2025). "The use of the Barh1 homeobox gene promoter to express tv-a was sufficient to produce medulloblastomas after intracerebellar delivery of the active N-terminal fragment of sonic hedgehog (SHH) and a stabilized N-myc proto-oncogene protein (MYCN) mutant in an RCAS vector." (PMID 36765816, 2023). "Cerebellar developmental tumors such as medulloblastoma are among the most common malignant pediatric brain tumors that originate from cerebellar GC precursor cells due to impairment of several molecular pathways, including SHH and MycN." (PMID 33804256, 2021). "In addition, amplification of CDK6, MYCN and SNCAP1 as well as aberrant ERBB4-SRC signaling and nuclear factor kappa B (NF-κB) have also been observed in Group 4 medulloblastoma." (PMID 33869004, 2021). "Since the WTC10 MYCN and Gorlin tumors both aligned with SHH medulloblastoma, we sought to determine whether NES cells were committed or “primed” to be in a GNP-like state." (PMID 31204176, 2019). "The SHH subtype also harbors MYCN-amplified (7.7–16.7%) and MYCL-amplified tumors (2.3%), although the biological role of L-MYC in medulloblastoma is unknown." (PMID 28587062, 2017). "Additionally, forced expression of wild-type MYCN can promote SHH-independent medulloblastoma development when driven from the brain-specific Glutamate transporter 1 (Glt1) promoter in the Tet-inducible Glt1-tTA;TRE-MYCN/Luciferase (GTML) transgenic model." (PMID 28333115, 2017). "We corroborated the microarray data with qRT-RTPCR in 12 primary medulloblastomas and determined that MYCN was not significantly overexpressed in tumors with gain or amplifications of 2p, compared to others (p = 0.31)." (PMID 16968546, 2006). "In addition, recent studies in medulloblastoma have shown that, although not the most commonly used marker, the genomic amplification of MYCN can be used during diagnosis." (PMID 39851951, 2025). "Among those tumors, medulloblastoma is grouped into four distinct molecular subgroups in terms of gene expression patterns, one of which is SHH group, in which the amplifications of MYCN and MYCL are most frequently observed, defining its pathological significance in medulloblastoma." (PMID 38884091, 2024). "However, sonidegib did not affect the proliferation of medulloblastoma with MYCN amplification or SUFU deletion." (PMID 35163655, 2022). "For example, the GTML (Glt1-tTA/TRE-MYCN-Luc) model in which MYCN aberration is driven by the glutamate transporter 1 (Glt1) promoter expressed in hindbrain progenitors develops tumors that closely resemble Group 3, but also shows the features of WNT, SHH, and Group 4 medulloblastoma." (PMID 33869004, 2021). "Treatment of murine and human PDX medulloblastoma cell lines with the pan-HDAC inhibitor Panobinostat lead to significant decreases in cell viability, with the lowest IC50 (14.4nM) seen in Grp3 MYC-driven PDX cells, and a marginally higher IC50 (25.27nM) in Grp4 MYCN-driven PDX." (PMID 34195095, 2021). "Likewise, different SCLCs have amplified MYC, MYCN, or MYCL, and different medulloblastoma subgroups overexpress either MYC or MYCN but not both." (PMID 33425720, 2020).
medulloblastoma (continued). "MYC and MYCN amplification have been described as important negative prognostic factors in pediatric medulloblastoma, and the negative impact of MYC amplification could be confirmed in adults." (PMID 27781424, 2016). "Group 3 tumors account for 28% of all medulloblastomas, and conceptually it may be convenient to consider them as being associated with MYC amplification (not MYCN) but not exclusively." (PMID 25101241, 2014). "The potent effects observed on BCL2 and MYCN expression in our study highlight the potential therapeutic value of BET inhibitors in other solid tumors driven by high expression of these oncogenes, including small cell lung cancer, medulloblastoma, retinoblastoma, and rhabdomyosarcoma." (PMID 24009722, 2013). "Increase of MYCN expression has been reported in cancer with an aggressive course and poor prognosis, particularly that of neural origin, and also in neuroendocrine tumors including medulloblastoma, while there is not much evidence linking MYCN to glial-derived tumors." (PMID 33430425, 2021). "The 2021 WHO classification of tumors of the central nervous system (CNS) lists MYCN among the genes characteristically altered in diffuse pediatric-type glioma, spinal ependymoma, as well as SHH-activated and non-WNT/non-SHH medulloblastoma." (PMID 37407554, 2023). "Using Illumina methylation arrays, we identified 66 differentially methylated regions (DMRs) comparing human patient SHH medulloblastoma (amplified for MYCN) to normal cerebellum, whereas 130 DMRs were identified in WTC10 MYCN tumors (data not shown)." (PMID 31204176, 2019).